IL1B (interleukin 1 beta)
Diseases named in the same sentence as IL1B in open-access papers (continued):
Sharing a sentence is not in itself a finding about the gene and the disease.
Cachexia (continued). "In the present study, we describe an increase of the CD68+ myeloid population also in the liver, across the progression of cachexia, which may be the cause for increased IL‐1β protein secretion that can be detected in the circulation." (PMID 37177862, 2023). "To determine the relative functional significance of these inflammatory cytokines in CKD, we tested whether Il6, Tnfα or Il1β deficiency would affect the cachexia phenotype in CKD mice." (PMID 34302016, 2021). "Hypothalamic inflammation with increased IL‐1β levels also triggers the hypothalamic‐pituitary‐adrenal axis, resulting in increased release of glucocorticoids that promote the breakdown of adipose tissue and skeletal muscle, directly causing cachexia." (PMID 32142217, 2020). "Proinflammatory cytokines such as IL-6, IL-1β, TNF-α, and IFN-γ are associated with muscle wasting in both clinical and preclinical cancer cachexia." (PMID 40469669, 2025). "Interleukin 1 beta (IL-1β) is a proinflammatory cytokine responsible for muscle atrophy and lipolysis during malnutrition and cachexia." (PMID 38610941, 2024). "The CC genotype of the IL1B gene was characterized with 85.7% sensitivity and 58.5% specificity in the prediction of cachexia (AUC = 0.72; p < 0.0001)." (PMID 38610941, 2024). "An important phenomenon accompanying cachexia is the inflammatory process, during which the secretion of proinflammatory cytokines is observed, including IL-1β, Il-6, IL8, TNF-α, and interferon-gamma (INF-γ)." (PMID 38610941, 2024). "Conversely, in patients with the Sarcopenia/Cachexia phenotype, we observed significantly decreased abundance of IL-1β and IL-2." (PMID 39575261, 2024). "Underlying the pathogenesis of cachexia are many inflammatory cytokines such as tumor necrosis factor‐alpha (TNF‐α), interleukin‐1beta (IL‐1β), and interleukin‐6 (IL‐6), which cause malnutrition and loss of skeletal muscle mass." (PMID 39229565, 2024). "The mRNA was isolated from mouse kidneys and was used to examine the expression levels of signaling proteins, inflammatory cytokines, and genes responsible for inducing cachexia (IL-1β, IL-6, TNF-α, TGF-β, GDF-15, and MYD88)." (PMID 39394174, 2024). "In conclusion, our results demonstrate for the first time, to the best of our knowledge, that the inflammasome pathway plays a role in the liver in cachexia, eliciting IL‐1β maturation." (PMID 37177862, 2023). "Proinflammatory cytokines, particularly TNF-α, IL-6, and IL-1β, are considered to be important mediators of cachexia induction." (PMID 37446099, 2023). "Several studies have demonstrated that chemotherapy-induced cachexia or CRF is associated with an increase in proinflammatory cytokines, such as TNF-α, IL-6, and IL-1β." (PMID 37699022, 2023). "In current clinical studies, good progress has been made in improving cachexia with therapies that counteract key cachexia factors such as IL-6, IL-1β, and IL-1α." (PMID 35740622, 2022). "In conjunction with its role as a cachexia mediator, IL-1β impairs immune function in multiple ways including the stimulation of myeloid-derived suppressor cells (MDSCs) and the induction of IL-6 and IL-22 expression." (PMID 35743911, 2022). "These and many other reports formed the precedent for the study on IL-1β in the development of illness behaviors and cachexia over the past two decades." (PMID 34439145, 2021). "Parameters of cachexia phenotype were completely normalized in Il1β−/−/CKD mice but were only partially rescued in Il6−/−/CKD and Tnfα−/−/CKD mice." (PMID 34302016, 2021). "Based on the rescue of CKD phenotype in Il1β−/− mice, we tested the efficacy of anakinra as a therapy for cachexia using a CKD mouse model." (PMID 34302016, 2021). "TNFα, IL-6, IL-8, IL-1β, and IFNγ are considered to be the major inflammatory mediators of cancer-induced cachexia, which have been demonstrated to be elevated in various animal models of cancer." (PMID 32722688, 2020).
Cachexia (continued). "We also evaluated expression of IL-6, TNF-α, IFN- γ, IL-1α, and IL-1β because these inflammatory cytokine are frequently observed in cachexia as well as fibrotic diseases." (PMID 32973293, 2020). "Higher levels of IL-6, IL-8, IL-1β and TNFα have been demonstrated in patients with confirmed cachexia." (PMID 33327591, 2020). "It is well-established that C26 cachexia alters the plasma levels of several soluble factors including TNFα, IL-1β and IL-6 which can accelerate the activity of key proteolytic pathways involved in the development of muscle weakness." (PMID 33014286, 2020). "Consistent with prior studies, KxPxCx allograft-induced cachexia resulted in hypothalamic inflammation in vehicle-treated animals, with increases in expression of Selp, Il1b, Il1r1, Tlr7, Ccl2, and Icam1." (PMID 31615993, 2019). "We found that serum TNFα and IL-6 levels were elevated in wild-type LLC tumor-bearing mice that developed cachexia, while IL-1β level remained unchanged." (PMID 28536426, 2017). "We thereby measured serum levels of TNFα, IL-6 and IL-1β in LLC tumor-bearing mice during the development of cachexia on days 0, 7, 14 and 21 of tumor implant as well as that of Hsp70/90 and EVs." (PMID 28928431, 2017). "Earlier studies have shown that ApcMIN mice exhibit uncontrollable systemic elevations in inflammatory factors IL-6, IL-1b, and TNF-a, with these same factors also associated with cachexia in patients." (PMID 26933816, 2016). "On the other hand, in a study of the pathophysiology of cachexia in patients with prostate cancer, a serum cytokinome profile of 10 biomarkers (IL-1β, IL-2, IL-4, IL-5, IL-6, IL-8, IL-10, IL-12, IFN-γ, and TNF-α) was evaluated." (PMID 28050120, 2016). "Herein, we describe a protective mechanism where IL-1β production after acute muscle injury or in cachexia drives increased C/EBPβ expression in muscle SCs, rendering SCs more resistant to apoptosis." (PMID 26913600, 2016). "It is tempting to speculate that this individual may have had cachexia at the time of sample collection where weight loss due to the increased glucose, lipid, and protein requirements of the tumor could manifest as low BMI compounded with elevated urinary IL-1β as a result of advanced disease." (PMID 25403235, 2014). "Muscle IL-1β, a predictor of cachexia and higher mortality rates in patients with PDAC, was the only consistent parameter that was increased in both muscles under study and might have triggered acute phase reaction leading to cachexia." (PMID 36979889, 2023). "These CCR1+ macrophages expressed cachexia mediators Tnf, Il1b, and Il6." (PMID 35031523, 2022). "Further, cancer cachexia is a complex phenomenon and targeting IL-1β in isolation may be insufficient but combined with a background standard of cachexia care, it may have its most optimal effect." (PMID 33907915, 2021). "The role of IL-1β in cachexia is further demonstrated by cachexia studies in which MyD88, which is the universal adaptor protein to all Toll-like receptors (TLRs; except TLR3) and the interleukin 1 receptor family, is implicated in the pathogenesis of cancer cachexia." (PMID 34439145, 2021). "Indeed, elevated circulating concentrations of TNF-α, IL-1β and IL-6 have been described in patients with cachexia." (PMID 32024569, 2020). "One hypothesis is that altered IL-1β levels might change neuroendocrine pathways leading to anorexia and thus, cachexia in ATTRv patients." (PMID 31253122, 2019). "Known factors involved in cachexia, IL-1α, IL-1β, IL-6, IL-8 and TNFα are all proteins that may be produced by the innate immune cells or other non-immune cell types such as epithelial cells or stromal cells." (PMID 30513792, 2018). "Notably, the cachexia-associated, pro-inflammatory TNF was upregulated 2.9-fold after weight loss, while expression of all interleukins (IL1B, IL6, IL10), as well as CCL3 was much lower than in the lean group." (PMID 27900559, 2017).
Cachexia (continued). "Interestingly, muscle IL-1β and SOCS3 gene expression were associated with several indices of cachexia, and several of these associations were altered by PDTC treatment." (PMID 27449092, 2016). "Mice genetically depleted for TGF-β1 succumb to a wasting syndrome and systemic inflammation, which is characterized by increased levels of cytokines (e.g. IL-1β), increased numbers of circulating neutrophils and monocytes and tissue infiltrating leukocytes (particularly heart, lung and stomach)." (PMID 23505428, 2013). "The central roles for IL-1β in the occurrence of cachexia have been demonstrated by many studies." (PMID 17359523, 2007). "As to IL-1B+3594 polymorphism, IL-1B+3594 T allele was seen significantly more frequently in the patients with cachexia than without (χ2 = 5.556, P = 0.018)." (PMID 17359523, 2007). "Patients with cachexia showed a significantly higher prevalence of IL-1B+3954 T allele than those without (P = 0.018)." (PMID 17359523, 2007). "Also, other cachexigenic factors besides IL-1Ra and IL-1β may control IL-6 production and induce cachexia in this model." (PMID 33557173, 2021). "However, the distribution of cytokine polymorphisms within the patients varied, with IL-1B+3954 T allele being found significantly more frequently in the cachexia patients than in non-cachexia patients (P < 0.05)." (PMID 17359523, 2007). "Ghrelin also acts via GH-independent pathways to suppress the pro-inflammatory and catabolic milieu that drives cachexia as it stimulates the release of the anti-inflammatory cytokine IL-10 while reducing levels of TNF-α, IL-1β, and IL-6." (PMID 40869331, 2025). "Systemic inflammation is one of the important characteristics of cancer cachexia, and inflammatory cytokines IL-1β, IL-6, and TNF-α in the serum of cancer cachexia patients have been confirmed." (PMID 37190306, 2023). "The separate stimulation of TNF and IL-1β promoted the secretion of LIF and IL-6 in a cachexia study with tumor-bearing mice, resulting in a synergistic effect." (PMID 35740622, 2022). "Inflammatory cytokines such as IL-6, IL-1β, and TNF-α are boosted in the TME in patients with systemic or cachexia." (PMID 36119037, 2022). "The searches for IL-1β, IL-6, TNF, and JAK were based on reports that these were involved in cancer cachexia syndromes." (PMID 36358681, 2022). "Previous studies have identified several cachexia-related cytokines, including interleukin-6 (IL-6), tumor necrosis factor alpha (TNF-α), IL-1β, and the leukemia inhibitory factor (LIF)." (PMID 35740622, 2022). "In this study, we showed that skeletal muscle IL-1β level was significantly increased in CKD mice, and Il1β−/− mice had attenuated CKD induced cachexia." (PMID 34302016, 2021). "In conclusion, the role of CRC cells is related to the production of classic cachexia-inducing factors (e.g., PIF, IL-6 and IL-6R, TNF-α, IL-1β, IL-1R1, and LIF), as well as novel factors known as “cachexokines”." (PMID 33557173, 2021). "The increased production of proinflammatory cytokines, mainly IL-1β and TNF-α, seems to be involved in inflammatory cachexia and induces the production of prostaglandin E2 (PGE2), which plays an important role in the inflammatory response." (PMID 26064425, 2015). "In addition, several proinflammatory factors, such as TNFα, IL-1β, and IL-6, are increased in WAT during cachexia, as a result of both adipocyte secretion and immune cell infiltration." (PMID 41373779, 2025). "Furthermore, several molecular signatures observed in the medial basal hypothalamus during cachexia are also found in the peripheral tumour microenvironment, such as CCR1+ macrophages expressing TNF, IL-1β, and IL-6." (PMID 40362192, 2025). "Moreover, in the course of cachexia, browning of adipose tissue is observed, which is mainly mediated by proinflammatory cytokines, e.g., TNF-α, IL-6, and IL-1β." (PMID 38610941, 2024).
Cachexia (continued). "The present study reports, for the first time, a significant increase in myocardial MAO-A expression with PDAC (-related cachexia) in combination with increases in the percentage of atrogin+-, IL-1β+-, and COX2+-cells as well as in related transcripts of IL-1β, COX2, TNF, and SOCS3 genes." (PMID 39335522, 2024). "In the piglet model with LPS-induced cachexia, the morphological and ultrastructural damage, and the release of pro-inflammatory cytokines including tumor necrosis factor (TNF)-α, interleukin (IL)-1β, and IL-6 were dynamically elicited in longissimus dorsi muscle." (PMID 37446099, 2023). "As a serious adverse HH effect in the context of cachexia that is not described before, it occurred despite the observed significant reduction in the likely pro-cachectic IL-1β mRNA expression in gastrocnemius muscle." (PMID 36979889, 2023). "IL-1α, TNF, IL-8, and IL-10 were significantly elevated in cachexia patients but IL-1β and IL-6 were not significantly elevated in the cachexia patients." (PMID 36358681, 2022). "Of the inflammatory cytokines produced peripherally and centrally during cachexia, possibly no other is more studied than IL-1β." (PMID 34439145, 2021). "Importantly, the cachexia phenotype was completely normalized in Il1β−/−/CKD mice relative to Il1β−/−/Sham mice whereas Il6−/−/CKD and Tnfα−/−/CKD mice still exhibited some degree of cachexia." (PMID 34302016, 2021). "The levels of serum IL-6 and IL-1β in the group receiving high-dose docetaxel increased, whereas the levels of TNF-α in all groups were more or less the same, suggesting that the docetaxel-induced cachexia differs from the tumor-induced cachexia." (PMID 25797259, 2015). "Overexpression of IL-1β in the ARC of arthritic rats on all dietary regimes indicates its role in AA- induced cachexia rather than anorexigenic neuropeptides CART and POMC." (PMID 20953376, 2010). "Since IL-1β up-regulates the transcription of pro-inflammatory genes by stimulating NF-κB phosphorylation or inhibiting p65NF-κB methylation, we similarly assessed the activities of NF-κB pathway in the settings of adipose wasting in LLC and C26-derived cancer cachexia models." (PMID 36581870, 2022). "However, inflammatory cytokines associated with cachexia, including tumor necrosis factor (TNF), interleukin (IL)-6, IL-1β, and interferon (IFN)-γ, are unlikely to be considered potential biomarkers associated with cachexia." (PMID 33731895, 2021). "In contrast, a recent report demonstrated that genetic deletion Il-1β failed to improve fatigue symptoms in several different rodent models of cancer, suggesting that, while IL-1β signaling may initiate or drive some cachexia symptoms, it is unlikely to be an all-encompassing therapeutic target." (PMID 34439145, 2021). "To evaluate local inflammation in skeletal muscle from PDAC patients with or without cachexia, we performed qRT‐PCR to examine mRNA expression of inflammatory cytokines tumour necrosis factor‐alpha (TNF‐α), interleukin‐6 (IL‐6), and interleukin‐1beta (IL‐1β)." (PMID 38725139, 2024). "From this profile, when compared to that of the control group, it appears that serum levels of all cytokines were significantly higher in the cachexia group, and six cytokines (IL-1β, IL-2, IL-8, IL-12, TNF-α, and IFN-γ) were significantly higher in the group with advanced Pca without cachexia." (PMID 28050120, 2016).
glioblastoma (73 papers, 2010 to 2025). The most malignant astrocytic tumor (WHO grade IV). "The results of the ROC, AUC, and RR analysis of IL-1β, IL-6, IL-8, and IL-10 indicated a potential diagnostic value for clinical prognosis in patients with glioblastoma (RR > 2)." (PMID 38003396, 2023). "The progression of glioblastoma in susceptible to hypoxia Wistar rats leads to the death of animals and is accompanied by an increase in the IL-1β level." (PMID 37542119, 2023). "The progression of glioblastoma 101.8 in susceptible to hypoxia Wistar rats was characterized by high mortality and an increase in the IL-1β level." (PMID 37542119, 2023). "EGFR variant III (EGFRvIII) was found to potentiate IL-1β-induced IL-6 secretion through the p38 MAPK-MK2-HuR pathway in glioblastoma cells." (PMID 31772161, 2019). "It has also been reported that IL-1β induces the apoptosis of cells of the glioblastoma cell line GL15 by causing an imbalance between the MAPK and SAPK pathways." (PMID 25544775, 2015). "Furthermore, glioblastoma cells release CCL13 in response to IL1β secretion by tumour-associated macrophages (TAMs), leading to monocyte recruitment and their differentiation into TAMs." (PMID 39315158, 2024). "Specific features of glioblastoma 101.8 progression in tolerant and susceptible to hypoxia rats, including survival, tumor growth rates and IL-1β level, can become the basis of new personalized approaches for cancer diseases treatment in accordance to individual hypoxia resistance." (PMID 37542119, 2023). "As IL-1β and IL-6 are associated with glioblastoma angiogenesis, we confirmed that KDELC2 suppression could inhibit the expression of some angiogenic factors, such as FGF and VEGF." (PMID 37107298, 2023). "Here, we expand on these findings as we delineate the signaling mechanism whereby treatment with IL-1RA quells IL-1β’s dramatic effect toward glioblastoma pathogenesis and spread." (PMID 40725140, 2025). "Elevated proliferation of U87 glioblastoma cells was noted 24 h after exposure to 50 ng/mL of IL-1β." (PMID 40725140, 2025). "In this study, we discovered that IL-1β plays a profound role in facilitating the growth and metastatic potential of glioblastoma via IL-1β’s role in activating the TLR-MyD88-NFkB pathway." (PMID 40725140, 2025). "The NLRP3 downstream effectors, IL-1β and NF-κB, are abundantly present in the tumor microenvironment of glioblastomas, contributing to their development." (PMID 38461458, 2024). "The model for IL-1β, including NLR (AUC = 0.907, Cut-off 0.473, Classifier accuracy 85.6%), showed a high diagnostic potential in glioblastoma and confirmed an implication of IL-1β in neutrophils recruitment and tumor promotion." (PMID 38003396, 2023). "Specifically, the transcription and translation of CH25H have been found to increase in response to TNFα and IL1β in glioblastoma cell lines." (PMID 37208656, 2023). "Blocking an inflammatory cytokine (IL-1β) thatdiverts self-aggravating inflammation andreduces glioblastoma aggressiveness." (PMID 37645153, 2021). "IL-1β knockdown slightly increased phosphorylated IκBα protein levels in RSL3-treated glioblastoma cells." (PMID 34987700, 2021). "Both the bone marrow as well the cord blood MSCs not only inhibited tumor growth, but also decreased angiogenesis in glioblastoma cell lines involving IL1β, FAK, and AKT pathways." (PMID 34944000, 2021). "We previously reported that IL-1β expression was upregulated by IL-20 in glioblastoma cells and oral cancer cells." (PMID 32929072, 2020). "Our data suggest that NLRP3 activation through LPS/Nigericin treatment leads to a high level of IL-1β and IL-18 secretion in prostate cancer and glioblastoma cell lines compared to cell lines derived from lung cancer, breast cancer, and neuroblastoma." (PMID 33613529, 2020). "Studies demonstrated that IL-1β induced hypoxia in glioblastoma and modulates the tumor progression by interacting directly with the tumor cells." (PMID 33613529, 2020).